GDF15 (growth differentiation factor 15)
Diseases named in the same sentence as GDF15 in open-access papers (continued):
Sharing a sentence is not in itself a finding about the gene and the disease.
pancreatic cancer (continued). "After overexpression GFRAL in pancreatic cancer cells, the effect of GDF-15 was significantly enhanced." (PMID 33201838, 2020). "Our results suggest a novel solid stress signal transduction mechanism bringing GDF15 to the centre of pancreatic tumor biology and rendering it a potential target for future anti-metastatic therapeutic innovations." (PMID 30700740, 2019). "Subsequently, GDF15 is secreted and acts in an autocrine manner to promote pancreatic cancer cell migration possibly through Akt activation." (PMID 30700740, 2019). "Performing a phosphoprotein screening, we identified that solid stress activates the Akt/CREB1 pathway to transcriptionally regulate GDF15 expression, which eventually promotes pancreatic cancer cell migration." (PMID 30700740, 2019). "With regard to cell migration, our results show that MIA PaCa-2 cells lacking GDF15 have reduced migratory ability indicating that GDF15 is critically involved in solid stress-induced pancreatic cancer cell migration." (PMID 30700740, 2019). "We conclude that solid stress signal transduction is mediated by an Akt-dependent mechanism that eventually promotes GDF15-induced pancreatic cancer cell migration." (PMID 30700740, 2019). "Further research on the role of GDF-15 and lysine/fat consumption, in the context of pancreatic cancer cachexia, is required." (PMID 31323984, 2019). "We have previously shown that RON P5P6 isoform is oncogenic, TNFRSF6B (DcR3 protein) prevents TRAIL induced apoptosis and GDF15 (MIC-1 protein) is being investigated as a highly specific marker of pancreatic cancer." (PMID 27323855, 2016). "In contrast, in pancreatic cancer patients GDF15 concentrations were about four to sevenfold higher (80 patients: 2.43 ± 2.32 ng/ml; corresponding to 194.24 ± 185.45 fmol/ml), or (50 patients: 5.39 ± 3.72 ng/ml; equivalent to 430.86 ± 297.36 fmol/ml)." (PMID 25823874, 2015). "Another microarray study of pancreatic cancer showed that GDF15 was regulated by both HOTAIR and PRC2." (PMID 25428914, 2015). "Two publications of the same group analysed GDF15 serum concentrations in pancreatic cancer patients by ELISA 26,35." (PMID 25823874, 2015). "Recent studies proposed GDF15 as a prognostic marker for ovarian and pancreatic carcinoma, two types of malignancies with frequent aneuploidy and chromosomal instability." (PMID 24548329, 2014). "Increased circulating levels of GDF15 have been reported in patients with breast, prostate, ovarian, and pancreatic cancers, including elevated serum levels of GDF15 reported in 6 of 10 (60%) metastatic breast carcinomas." (PMID 23227361, 2012). "Although it was not shown whether this co-expression is also existent in normal tissues, this constellation strongly argues for carrying out feedback sensing of autocrine-released GDF15 from pancreatic cancer cells." (PMID 38474863, 2024). "However, the direct association between GDF-15 and GFRAL was only demonstrated in pancreatic cancer." (PMID 39000420, 2024). "In addition, combined anti-GDF-15 and anti-PD-1 therapy results in increased T lymphocyte infiltration in mouse models of pancreatic cancer." (PMID 39000420, 2024). "Finally, we systematically described the characteristics, mechanism of action, and clinical value of GDF-15, aiming to provide help for the detection and treatment of pancreatic cancer." (PMID 38335385, 2024). "Both the MAPK/ERK pathway, in brain cancer cell lines, and the PI3K/AKT pathway, in pancreatic cancer cell lines, increase the expression of the migration-related GDF15 (growth/differentiation factor 15) gene which mediates cancer cell migration after their compression." (PMID 37364915, 2023). "Hence, we sought to investigate that if NR5A2 promotes pancreatic cancer cell malignancy by activating GDF15 expression." (PMID 33850096, 2021). "Indeed, BRD4 overexpression in pancreatic cancer cells increased GDF15 expression at both the mRNA and protein levels; this effect was reversed by NR5A2 silencing." (PMID 33850096, 2021).
pancreatic cancer (continued). "Notably, BRD4 inhibition in pancreatic cancer downregulated GDF15 at the mRNA and protein levels, and GDF15 expression was recovered by NR5A2 silencing." (PMID 33850096, 2021). "Furthermore, GDF15 silencing attenuated cell proliferation, invasion, and wound healing ability in pancreatic cancer cells overexpressing NR5A2." (PMID 33850096, 2021). "In turn, NR5A2 activates the transcription of GDF15, promoting pancreatic cancer progression." (PMID 33850096, 2021). "On the other hand, we also found GDF-15 was upregulated in pancreatic cancer plasma and tissues." (PMID 33201838, 2020). "GDF15 also augmented the invasive potential of cancer cells, and the analysis of breast cancer tissues showed a significant relationship between p38 activation and cisplatin resistance and increased invasiveness in pancreatic cancer." (PMID 32046099, 2020). "In vitro, we found that GDF-15 promotes the proliferation of several pancreatic cancer cell lines." (PMID 33201838, 2020). "Secreted GDF-15 could inactivate tumor infiltrating macrophages, thus evading macrophage immune surveillance and allowing the expansion of pancreatic cancer." (PMID 33201838, 2020). "Additionally, he showed that growth differentiation factor 15 (GDF‐15) is required for development of pancreatic cancer KPP and GDF‐15fl/fl mice exhibit a reduction in pancreatic cancer." (PMID 32049447, 2020). "GDF-15 expression strongly correlated with poor prognosis for pancreatic cancer patients." (PMID 33201838, 2020). "GDF-15 protein enhanced tumor cell proliferation in two pancreatic cancer lines, AsPC-1 and BxPC-3." (PMID 33201838, 2020). "These novel findings could possibly give an explanation for the elevated GDF15 levels observed in the serum of patients with solid tumors, such as in the case of breast, prostate and pancreatic cancer that exhibit high solid stress levels." (PMID 30700740, 2019). "In our previous work, we showed that solid stress activates normal pancreatic fibroblasts enabling them to promote pancreatic cancer cell migration through the secretion of Growth Differentiation Factor-15 (GDF15), which is strongly elevated in fibroblasts as a response to mechanical compression." (PMID 30700740, 2019). "Interestingly, however, treatment with rhGDF15 managed to completely reverse this inhibitory effect, clearly suggesting that GDF15 plays a crucial role in solid stress-induced pancreatic cancer cell migration." (PMID 30700740, 2019). "Among malignancies, GDF-15 has been shown to be strongly expressed in prostatic, pancreatic, colorectal, gastric, urothelial, and renal carcinomas as well as melanoma, and at relatively lower levels, in cervical, breast, endometrial, thyroid, and pancreatic carcinomas." (PMID 37905271, 2023). "However, association between GDF15 level and weight loss was only confirmed in patients with lung but not pancreatic cancer." (PMID 33925872, 2021). "Hence, we hypothesized that BRD4 upregulated GDF15 by inducing NR5A2 expression in pancreatic cancer." (PMID 33850096, 2021). "Similarly, in pancreatic cancer, an analysis based on 108 gene expression profiles from the TCGA database found a correlation between high GDF-15 expression and poor survival; however (possibly due to the generally dismal prognosis), this finding was not statistically significant (p = 0.105)." (PMID 32508832, 2020). "GDF-15 is upregulated in many types of cancers, such as glioblastoma, testicular cancer, ovarian cancer, oral squamous cell carcinoma, uveal melanoma, hepatocellular carcinoma, lung cancer, prostate, breast, colon, and gastric cancer, including pancreatic cancer." (PMID 33201838, 2020). "GDF-15 overexpression has been observed in several types of tumor disease, such as glioblastoma, testicular cancer, ovarian cancer, oral squamous cell carcinoma, uveal melanoma, hepatocellular carcinoma, lung cancer, prostate, breast, colon, and gastric cancer, including pancreatic cancer." (PMID 33201838, 2020).
pancreatic cancer (continued). "In the organoids produced by pancreatic cancer patients, LIF, IL-8, and growth differentiation factor 15 (GDF15) are prominently up-regulated in cachectic patients." (PMID 35740622, 2022). "NR5A2 overexpression induced by BRD4 enhanced the transcription of GDF15 in pancreatic cancer, suggesting that BRD4/NR5A2/GDF15 axis is a potential therapeutic target in pancreatic cancer." (PMID 33850096, 2021). "IHC analysis on a TMA of pancreatic cancer samples indicated that there exists a positive correlation between the expression of NR5A2 and GDF15." (PMID 33850096, 2021). "Therefore, NR5A2 and GDF15 could be promising therapeutic targets in pancreatic cancer." (PMID 33850096, 2021). "To test if NR5A2 promotes the progression of pancreatic cancer via GDF15, we first carried out MTS, colony formation, and transwell invasion assays in pancreatic cancer cells after GDF15 silencing or overexpression." (PMID 33850096, 2021). "The newly identified GDF-15/GFRAL axis provides a vital and novel potential biomarker for diagnosis and therapeutics in pancreatic cancer." (PMID 33201838, 2020). "In pancreatic cancer microenvironment, solid stress can activate Akt/CREB1 signaling pathway to upregulate GDF-15 expression, which eventually promotes tumor cell migration." (PMID 33201838, 2020). "However, the receptor of GDF-15 in pancreatic cancer cell remains unclear." (PMID 33201838, 2020). "However, GDF-15 has not been extensively researched in association with pancreatic cancer but may be influenced by lysine-deficiency and chronic high-fat consumption." (PMID 31323984, 2019). "We also found that Growth Differentiation Factor 15 (GDF15) expression and secretion is strongly upregulated in pancreatic cancer cells in response to mechanical compression." (PMID 30700740, 2019). "Finally, we analyzed the correlation between GDF-15 and GFRAL in 13 pairs of pancreatic cancer blood and tissues." (PMID 33201838, 2020). "Knockdown of expression of either GDF15 or FABP3 using specific siRNA in AsPC-1 cells reversed the growth inhibitory effects of frondoside A. These findings suggest that both GDF15 and FABP3 are involved in the growth inhibitory effects of frondoside A in pancreatic cancer." (PMID 29463049, 2018). "In this study, we showed that NR5A2 promoted pancreatic cancer progression by inducing GDF15 expression, suggesting that the pro-tumorigenic roles of NR5A2 and BRD4 in pancreatic cancer could be reversed by GDF15 inhibition, making GDF15 a promising therapeutic target." (PMID 33850096, 2021). "To explore whether GDF-15 plays a biological role in pancreatic cancer tissues by means of GFRAL, we performed dual immunofluorescence staining assay to detect the localization of GDF-15 and GFRAL, and found that both protein molecules are co-expressed in pancreatic ductal epithelial cancer cells." (PMID 33201838, 2020). "We also found that GDF-15 could induce pancreatic cancer cell lines AsPC-1, BxPC-3, but not Panc-1 or Hs766t to proliferate." (PMID 33201838, 2020). "However, the mechanism by which GDF15 is regulated in response to mechanical cues as well as the way by which it can promote solid stress-induced pancreatic tumor progression are not yet fully defined." (PMID 30700740, 2019). "Furthermore, GDF15 promoted the proliferation of cervical cancer cells by interaction with ErB2 to activate PI3K/AKT and MAPK/ERK pathways, and enhanced the migration of pancreatic cancer cells via an AKT pathway." (PMID 31861872, 2019). "A pancreatic cancer genomic analysis of pterostilbene revealed downregulation of multiple apoptosis-related genes including MnSOD, DNA-damage-inducible transcript 3 (DDIT-3), and growth differentiation factor 15 (GDF-15), also known as macrophage inhibitory cytokine 1 (MIC-1)." (PMID 23691264, 2013).
pancreatic cancer (continued). "Furthermore, we show that compressed MIA PaCa-2 cells lacking GDF15 (either after shGDF15 or siGDF15 treatment) exhibited reduced migratory ability while treatment with rhGDF15 reversed this effect, suggesting that GDF15 plays a crucial role in solid stress-induced pancreatic cancer cell migration." (PMID 30700740, 2019). "As we all know that GDF15, as an important component of the TGF-β superfamily, is notably increased in patients with prostate, colorectal, or pancreatic cancers and has been described as an important biomarker of poor clinical outcome." (PMID 27643489, 2016).
anemia (45 papers, 2009 to 2025). A reduction in the number of red blood cells, the amount of hemoglobin, and/or the volume of packed red blood cells. "Further investigation revealed that anemia associated with chronic diseases and iron deficiency anemia independently induced a marked increase in GDF15." (PMID 39124668, 2024). "Research investigating the longitudinal associations between GDF-15, hepcidin, and Hb levels in older adults or exploring the therapeutic implications of targeting these pathways in the management of anemia and age-related diseases is furthermore needed." (PMID 38883134, 2024). "Serum GDF-15 levels are associated with all-cause mortality, and elevated plasma GDF-15 levels can predict the development of anemia in the elderly." (PMID 37755357, 2023). "In one cross-sectional study in South Africa, GDF-15 was found to be a predictor of iron deficiency anemia in early renal disease." (PMID 35251002, 2022). "Growth differentiation factor 15 is associated not only with decreased muscle performance, increased inflammation, anaemia, impaired renal functions, and metabolic disorders but also with age‐related sarcopenia." (PMID 34939349, 2022). "Enhanced hepcidin production has been implicated in the pathogenesis of anemia in chronic inflammatory disorders like HF, and GDF-15 was recently identified as a hepcidin-suppression factor." (PMID 34611778, 2022). "Plasma GDF-15 levels have been found to be high in iron deficiency anemia, anemia of chronic disease and iron overloading anemia such as β-thalassemia." (PMID 35251002, 2022). "GDF-15 was inversely associated with several indices of anemia and correlated positively with ferritin." (PMID 34611778, 2022). "At least several additional papers support the finding that GDF-15 levels increase with age, and elevated GDF-15 levels are associated with the development of anemia in older adults." (PMID 35821815, 2022). "First, the cross-sectional study design makes it difficult to infer causality between hepcidin, GDF-15 levels, and the risk of anaemia." (PMID 32993549, 2020). "Increased GDF-15 concentrations were associated with more advanced MM stage, anemia, renal impairment (lower glomerular filtration and higher markers of tubular injury), and inflammation." (PMID 33144847, 2020). "We analyzed the associations of serum GDF-15 with clinical characteristics of 73 MM patients (including asymptomatic MM) and the laboratory indices of renal function, anemia, and inflammation." (PMID 33144847, 2020). "GDF-15 was shown to have a role in normal erythropoiesis, and its expression was increased in erythroblasts from patients with refractory anemia, which is associated with large increase in iron in mitochondria." (PMID 30670947, 2018). "Research investigating the longitudinal associations between GDF-15, hepcidin, and hemoglobin levels in older adults or exploring the therapeutic implications of targeting these pathways in the management of anemia and age-related diseases is needed in the future." (PMID 38883134, 2024). "GDF-15 has also been associated with incident disability and incident anemia." (PMID 37982669, 2024). "Serum GDF-15 and hepcidin could potentially inform diagnostic or treatment strategies for anemia or age-related health conditions." (PMID 38883134, 2024). "Our study, therefore, suggests that GDF-15 can be a useful diagnostic tool in patients with anemia." (PMID 37649102, 2023). "In prior studies, GDF15 was significantly and inversely associated with testosterone level in subjects with anaemia, as well as estradiol could activate GDF15 expression in the tamoxifen resistant cell systems." (PMID 36635686, 2023). "From our results, the high ferritin levels associated with CRP and GDF-15 may indicate the link between iron homeostasis and the inflammatory response through anemia of inflammation or chronic disease." (PMID 37649102, 2023).